CD4 (CD4 molecule)
Diseases named in the same sentence as CD4 in open-access papers (continued):
Sharing a sentence is not in itself a finding about the gene and the disease.
COVID-19 (continued). "However, insufficient information directly examining SARS-CoV-2 antigen-specific CD4+ T cells, CD8+ T cells, and neutralizing antibodies in the same acute patients is hindering our understanding of the roles of adaptive immunity in acute COVID-19 protection or pathogenesis." (PMID 33010815, 2020). "In contrast, while we could not see any difference in the PD1 MFI on CD4+ T cells between COVID-19 patients and healthy donors, malaria patients showed a significantly increased PD1 MFI on bulk, naïve, and all CD4+ memory T cell subsets compared to healthy donors." (PMID 32983106, 2020). "In turn, we did not notice a difference in the CD4+/CD8+ ratio between severe and mild COVID-19 subgroups." (PMID 41157669, 2025). "Our findings are also novel in that in addition to lower CD4+ T cell count, we also demonstrated a relationship between higher HIV viral load and diminished COVID-19 vaccination response, which was not previously reported." (PMID 40432125, 2025). "When analysed in detail, a positive correlation between CD4+ PD-1 and CD8+ PD-1 was found in all COVID-19 groups but not in the control group." (PMID 40005306, 2025). "Upon further stratification into CD4 and CD8 subsets, while differences among the three groups persisted, direct comparisons between bacterial pneumonia and COVID-19 revealed no significant distinctions." (PMID 40370439, 2025). "Depending on the immunosuppression levels, a higher risk of hospitalization and mortality have been described for COVID-19 in people living with HIV (COVID/PLWH), mainly in those without antiretroviral therapy (ART) and with low CD4+ T cell count." (PMID 39861879, 2025). "Although the percentage of PD-1+ CD4+ T cells did not change in COVID-19+, the percentage of PD-1+ CD8+ T cells showed an increasing trend in COVID-19+ and negatively correlated with convalescence." (PMID 40698364, 2025). "Unlike CD4+ T cells, CD8+ T cells from LTBI/COVID-19 individuals exhibited increased degranulation capacity upon antigen-specific stimulation." (PMID 40458413, 2025). "For the α-chain V region gene segments, the healthy samples for CD4 and CD8 T cells clustered together, as did the PIMS-TS samples, but not COVID-19 samples." (PMID 40331338, 2025). "Unlike Pfizer, Moderna’s COVID-19 mRNA vaccine did not induce CD8+ T cells against spike peptides, although both triggered CD4+ T cell responses." (PMID 41157248, 2025). "Seroconversion rates and T-cell responses following COVID-19 vaccination can be highly variable in PLWH and are typically lower in individuals with low CD4 counts (<200 cell/μL) or who are not virally suppressed." (PMID 40463375, 2025). "At baseline, CD4+ and CD8+ naïve, stem cell-like memory, and central-memory T-cell subsets were not significantly different when comparing UN and COVID-19+ tissues." (PMID 40698364, 2025). "Our ultimate and long-term goal is to identify protective T cell antigens and epitopes that are preferentially recognized by CD4+ and CD8+ T cells from patients who have resolved acute COVID-19 and never developed LC (recovered asymptomatic patients)." (PMID 41157582, 2025). "Several studies also conclude limited to no increases in clinical severity with COVID-19 in people living with HIV, especially with normal CD4+ T lymphocyte counts due to effectively administered antiretroviral therapy." (PMID 39065058, 2024). "CD4 molecule also facilitate SARS-CoV-2 entrance into CD4+ T-cells, but not CD8+ T-cells, as it was detected in the blood of severe COVID-19 cases." (PMID 38965547, 2024). "Incomplete studies, studies not reporting any antibody level, and studies reporting CD4 and CD8 cell count in response to COVID-19 vaccination." (PMID 38721084, 2024). "In this context, reducing severe cases and deaths from COVID-19 also involvesproviding care to PLWH, especially those with low CD4+ T cell counts, high HIV viralloads, and not undergoing antiretroviral therapy (ART)." (PMID 39536214, 2024).
COVID-19 (continued). "In line with observations in memory CD4+ T cells, the autoreactive memory CD8+ T cell response was mostly found in non-COVID-19 (four out of seven) rather than post-COVID-19 (one out of four) patients with GBS." (PMID 38233524, 2024). "Patients in the non-COVID-19 group were younger and had a lower median CD4 + cell count during hospitalisation, a higher proportion of ADEs, and a lower proportion of VS upon admission than PWH in the COVID-19 group." (PMID 38789972, 2024). "Overall, the immune responses following COVID-19 vaccination in PWH appear to be comparable to those in people without HIV, except for individuals with CD4 counts below 200 cells/mm3 and detectable viremia." (PMID 37821620, 2024). "A study in Russia among 376 HIV/COVID-19 patients (171 without ART and 205 with ART) suggested that elevated anti-inflammatory markers such as IL-10 and TGFβ, reduced CD4+/CD8+ cell ratios led to an increase in exhausted T cells in ART naïve patients." (PMID 38628843, 2024). "Although this increase was observed in CD8+ T cells and not in CD4+ T cells, the augmented population of CD16+ T cells in BALF from patients with severe COVID-19 was further substantiated by data mining of scRNA-seq." (PMID 38607373, 2024). "Conversely, activated CD4 and CD8 cell counts increased in non-immunosuppressed patients with acute COVID-19, an effect that was reduced in the presence of immunosuppression." (PMID 38791279, 2024). "For this, we tested plasma from 37 COVID-19 samples with (n = 16) or without (n = 21) IgM ALAb, five HD, and two flu-infected individuals for their ability to induce CDC of HD CD4+, CD8+, or B lymphocytes." (PMID 38694513, 2024). "Anti-COVID-19 vaccines are, in general, safe and well tolerated, as well as immunogenic, in PWH unless they are viremic and immune non-responders (CD4+ T cell counts < 350 per mm3)." (PMID 39772034, 2024). "When analyzing the impact of COVID-19 severity, we found that hospitalized PWH had lower nonclassical (CD16+) monocyte frequencies, decreased expression of TIM3 on CD4+ T cells, and increased expression of PDL1 and CD69 on CD8+ T cells." (PMID 38408318, 2024). "First, the study of CCCs/SARS-CoV-2 cross-reactive memory CD4+ and CD8+ T cells in unvaccinated symptomatic and asymptomatic COVID-19 patients has not been adjusted retrospectively to previous CCCs infections, due to the lack of pre-COVID-19 samples." (PMID 38605956, 2024). "Such parameters included decreased percentages of CD3+CD4+ (Th) cells and increased percentages of CD3+CD8+ (Tc) cells in LN patients regardless of COVID-19 status." (PMID 39125849, 2024). "We observed that the frequencies of SARS-CoV-2 spike-specific CD4+ and CD8+ T cells were not significantly different between PLWH and controls after two doses of a COVID-19 vaccine." (PMID 38793543, 2024). "Overall, our findings demonstrated that, regardless of the time points along the timeline kinetics, CD4+CD38+ and CD8+CD69+ presented outstanding accuracy (AUC ≥ 0.9) in classifying COVID-19 patients vs. HCs." (PMID 39597661, 2024). "In our study, we also showed that lymphocyte counts in COVID-19 patients and the CD3+ and CD4+CD8+ subsets were significantly lower, especially in the non-survivor group." (PMID 36836679, 2023). "We analyzed the cytokine production capacity of circulating CD4+ and CD8+ T cells from the PBMCs of non-infected individuals, non-persistent patients and persistently infected COVID-19 patients at early time points of infection (≤10 DSSO)." (PMID 37529320, 2023). "We found that patients with severe COVID-19 and diabetes had greater frequencies of CD62L+ CD4+ T cells compared to diabetics with non-severe COVID-19 (p<0.01) and non-diabetics with non-severe (p=0.02) or severe disease (p=0.04)." (PMID 36817450, 2023).
COVID-19 (continued). "This prospective cohort study aimed to assess the humoral immune response to inactivated COVID-19 vaccination among PLWH compared to HIV negative controls (HNCs) and to determine the impact of CD4 cell count on vaccine response among PLWH." (PMID 36670363, 2023). "We used multiparameter flow cytometry to compare CD4+ and CD8+ T cell responses in severe (ICU admitted) and non-severe (admitted to observational unit) hospitalized COVID-19 patients." (PMID 36817450, 2023). "The median CD4 count among those infected with COVID-19 was 557 (IQR: 386–734) and the count among those PLHIV subjects not infected with COVID-19 was 516 (IQR: 366.75–728)." (PMID 38005865, 2023). "Although no subsequent literature has demonstrated COVID-19 vaccination-induced differential expression of RPL10, RPS3, and RPS4X in CD4+ T cells, these genes are still considered potent features." (PMID 36936955, 2023). "PD1+TIM3+CD4+ T cells and CXCL10 were significantly increased in female ICU but not male ICU patients compared with non-ICU COVID-19 patients." (PMID 37998327, 2023). "Here, we show that SARS-CoV-2 infects human CD4+ T helper cells, but not CD8+ T cells, and is present in blood and bronchoalveolar lavage T helper cells of severe COVID-19 patients." (PMID 37523305, 2023). "Several studies have reported that numbers of CD3+, CD4+ and CD8+ T cells were reduced in severe COVID-19 patients compared with non-severe or healthy patients." (PMID 37766091, 2023). "The study found no statistically significant variation in the population of CD4 and CD8 subsets of cells between day 1 and day 4 among COVID-19 patients with mild symptoms." (PMID 37465793, 2023). "This immune response includes superantigen-like activation of T-cells with expansion of polyclonal expansion of TCR Vbeta 21.3+ CD4+ and CD8+ T-cells, something which is not seen in toxic shock syndrome, Kawasaki disease or COVID-19 in general." (PMID 37550719, 2023). "The lack of overt changes to the magnitude of S-specific CD4 and CD8 T cell responses after extended prime-boost immunization protocols has also been observed in humans vaccinated with COVID-19 mRNA vaccines." (PMID 37243266, 2023). "Compared with COVID-19 patients without myocardial injury, the levels of IL6 in patients with myocardial injury increased, while the number of CD4+ T cells, CD8+ T cells, B cells, and NK cells decreased (P<0.05)." (PMID 37564653, 2023). "In COVID-19 convalescent patients, there was a significant correlation between the percentage of SARS-CoV-2 non-spike-specific CD4+ T cells and anti-spike RBD IgG." (PMID 37114058, 2023). "While there are no clearly-defined immune correlates of protection against COVID-19, there is considerable evidence that neutralizing antibodies, an elevated CD8+ T cell response and TH1-biased CD4+ effector responses provide optimal protective immunity." (PMID 35390102, 2022). "Frequencies of SARS-CoV-2-specific activated CD4+ T cells, irrespective of used SARS-CoV-2 antigen, were higher in the adults with moderate COVID-19 illness compared to adults with mild symptoms at T1." (PMID 35197982, 2022). "Enumeration of peripheral blood levels of SARS-CoV-2-S1/M-reactive IFN-γ CD4+ and CD8+ T cells does not predict viral clearance from the lower respiratory tract or poor clinical outcomes in critically ill COVID-19 patients." (PMID 35995830, 2022). "While co-culture of CD16Int LDN from COVID-19 patients stimulated proliferation of CD4+ and CD8+ T cells to the same degree as HD NDN, CD16Hi LDN and COVID NDN failed to stimulate CD8+ and CD4+ T cell proliferation." (PMID 35711435, 2022). "The expression of negative immune checkpoint molecules on CD8+ and CD4+ T cells examined in 14 individuals with severe COVID-19 revealed an increased abundance of PD-1 and TIM-3 levels in most severe COVID-19 cases." (PMID 36003367, 2022).
COVID-19 (continued). "In the setting of fatal COVID-19 and evolving ALI, alveolar epithelial cell depletion is primarily correlated with cytotoxic T cells and CD4+ macrophages, rather than age." (PMID 35446789, 2022). "Levels of total CD4+CXCR5+ Tfh cells were significantly increased in the non-diabetic COVID-19 patients compared with healthy volunteers (p = .003) and diabetic COVID-19 patients (p = .01)." (PMID 35286241, 2022). "From the present study, there were significant differences in lymphocytes, NLR, CRP, AST, Cr, CD3+ T cells, CD4+ T cells, CD8+ T cells, CD19+ T cells, and CD16+/CD56+ NK cells in mild/moderate COVID-19 cases with and without progression." (PMID 35619076, 2022). "We observed an increase in the percentage of CD4+ T lymphocytes and CD8+ T lymphocytes that express HLA-DR in COVID-19 patients, regardless of the severity of symptoms, compared to uninfected individuals." (PMID 36359755, 2022). "that enrolled 33 COVID-19 patients revealed negative correlations between the levels of CRP and CD3+, CD3+CD4 +, CD3+ CD8+ subpopulations of lymphocytes, which is consistent with our results." (PMID 35603207, 2022). "Among COVID-19-naive PWH, we initially observed a weak inverse correlation between recent CD4+ T-cell count and IgG half-life, but this was not significant after excluding an outlier with a long (>200 day) half-life." (PMID 36545783, 2022). "Although most COVID-19 survivors have specific T cell responses to SARS-CoV-2, the results from the virus-specific spike/control ratio of CD4+T cells and CD8+T cells in the five groups were not statistically significantly different." (PMID 35924252, 2022). "In one fatal COVID-19 case, the patient did not exhibit detectable SARS-CoV-2-specific CD4 + or CD8 + responses after 2 weeks post-symptom onset, highlighting the importance of mounting T cell responses during early infection." (PMID 36385011, 2022). "A lower frequency of CD4+CXCR5+ICOS+ Foxp3+ Tfr cells was found in the diabetic patients compared to controls (p = .01) and non-diabetic COVID-19 patients (p = .02)." (PMID 35286241, 2022). "Our results indicated higher expressions of CD95/Fas on memory (CD45RAneg) T cells, including both CD4 and CD8 T cells, which was not related to higher immune activation in COVID-19 patients as compared to HDs." (PMID 35066575, 2022). "DCs in the acute phase of COVID-19 failed to stimulate the proliferation of CD4+ and CD8+ T cells according to a mixed lymphocyte reaction assay with allogeneic CD4+ and CD8+ T cells." (PMID 35265087, 2022). "High frequencies of circulating SARS-CoV-2 specific CD4 and CD8 T-cells were detected in peripheral blood of the patient more than 200 days after recovery of COVID-19 (results not shown)." (PMID 35410137, 2022). "First it has been demonstrated that mild COVID-19 patients, who typically recover without special treatment, showed broad SARS-CoV-2-specific CD4+ T cell responses to S and N proteins, responses that were highly correlated with specific antibody titers." (PMID 35844575, 2022). "Strikingly, reductions in entropy and increases in dominance were now even more overt for those aged ≥50 y, being significant for CD4+ and CD8+ cells by all measures, whereas no significant changes were observed for patients with COVID-19 aged <50 y." (PMID 35943978, 2022). "In our cohort, CD3+ T cells, CD4+ T cells, CD8+ T cells, CD19+ T cells, and CD16+/ CD56+ NK cells showed significant differences in mild/moderate COVID-19 cases with and without progression." (PMID 35619076, 2022). "SARS-CoV-2-specific T cell responses were associated with a milder disease, but not neutralizing antibodies, indicating roles for both CD4+ and CD8+ T cells in protective immunity against COVID-19." (PMID 36447262, 2022). "All patients with IBD had similar frequencies of spike-specific CD4+ and CD8+ T cells after COVID-19 vaccination, irrespective of immune-modulating therapy." (PMID 35347100, 2022).
COVID-19 (continued). "There were no additional differences in the overall percentage distribution of NK, NK-like, CD4+ T, and CD8+ T lymphocytes between the control and COVID-19 groups or between COVID-19 ICU and non-ICU patients." (PMID 35741107, 2022). "On the contrary, the CD4+ (but not CD8+) T-cell proliferative response did not decline six months after the vaccine, but remained at the same high levels of the post-COVID-19 patients with pneumonia." (PMID 35744768, 2022). "CD4+ T cells and CD8+ T cells-mediated immune responses are present throughout the course of COVID-19 disease, but evidence of CD4+ T cells and CD8+ T cells in COVID-19 disease surveillance is still lacking in large samples." (PMID 35774402, 2022). "After accounting for effects of age and sex, ILCs, but not CD4+ or CD8+ T cells, were lower in individuals hospitalized with COVID-19 when compared with controls." (PMID 35275061, 2022). "The levels of S1-specific antibodies in vaccinees did not correlate with CD4+ or CD8+ T cell responses, whereas in COVID-19 patients anti-S1 IgG antibody levels had a trend with CD4+ (r=0.487, p=0.0667) and CD8+ (r=0.386, p=0.1551) T-cell responses." (PMID 35529867, 2022). "This cross-sectional study aimed to assess the humoral immune response to inactivated COVID-19 vaccination among PLWH compared to HIV negative controls (HNC) and to determine the impact of CD4 cell count on vaccine response among PLWH." (PMID 35794897, 2022). "In both HC and patients convalescing from COVID-19, but not donors with MIS-C, we observed a positive correlation between CD4+ T cell FC to SARS-CoV-2 MPs and the frequency of central memory CD4+ T cells." (PMID 35044955, 2022). "The concentration of CD4 cells and CD8 cells did not vary between COVID-19 affected individuals compared to normal healthy people." (PMID 35911334, 2022). "We found a similar result for CD69+ cells in both CD4 and CD8 lymphocytes in pregnant and nonpregnant COVID-19 patients." (PMID 35901034, 2022). "In convalescents, we did not detect any notable changes in the proportion of responders nor the magnitude of nucleocapsid-specific CD4+ and CD8+ T cells between individuals who experienced one or two COVID-19 episodes." (PMID 36584684, 2022). "For all non-naive CD4 T-cell subsets (primarily for EM1, EM2, and EM3), an increased number of both CD38+HLA-DR+ and also Ki-67+ cells were found in patients with COVID-19." (PMID 35632823, 2022). "Neither CD4+ T cells, CD8+ T cells, nor CD16+ NK cells were depleted in pediatric COVID-19 patients." (PMID 35275061, 2022). "The same applies in the case of ICU (intensive care unit) patients: total T-cell, CD4+ and CD8+ T-cell counts in peripheral blood were significantly lower than in non-ICU COVID-19 cases, and the counts correlated negatively with patient survival." (PMID 35833134, 2022). "A pharmacological inhibitor of TLR3 considerably reduced cytokine and chemokine production by CD4+ and CD8+ T cells but not by CD14+ monocytes, highlighting divergent signaling pathways of immune cells in response to COVID-19 plasma exosomes." (PMID 36526691, 2022). "Expression of PD1, ICOS, and CD38 were similar between COVID-19-naïve individuals with PAD syndromes and healthy donors at day 7 to 28 following vaccination, suggesting there was no defect in CD4+ T cell activation in most individuals with PAD syndromes." (PMID 36618402, 2022). "The lower CD4+ T cell proportions and higher CD8+ T cell proportions were observed in male and severe COVID-19 patients and the differences were independent of estrogen level." (PMID 33350432, 2021). "Unlike CD4+ T cells, many features of CD8+ T cell activation and proliferation were elevated compared to the healthy adult range at admission for pediatric COVID-19 and MIS-C patients." (PMID 33653907, 2021).